TNF (tumor necrosis factor)
Diseases named in the same sentence as TNF in open-access papers (continued):
Sharing a sentence is not in itself a finding about the gene and the disease.
schistosomiasis (continued). "For example, circulating cytokines interleukin-10 (IL-10) and tumor necrosis factor (TNF) are two biomarkers that have consistently been shown as elevated in human schistosomiasis." (PMID 30453907, 2018). "The RA vaccine model has also elucidated the important role of TNF-α in protection against schistosomiasis." (PMID 26945988, 2016). "In the chronic phase of schistosomiasis, TNF-α production was described as an important stimulator of nitric oxide production in response to the PIII-fraction of the soluble antigen of S. mansoni adult worms." (PMID 23270458, 2012). "Although the actual role of TNF-α in schistosomiasis is still debated, several lines of research have implicated this molecule in the chronic form of the disease." (PMID 21887276, 2011). "During pre-patent infection, several consistent trends were observed in the sputum, including an increase in pro-inflammatory cytokines such as IL-1 and TNFα, warranting further studies of the respiratory response during pre-patent schistosomiasis, with an increased sample size." (PMID 37012228, 2023). "In conclusion, these results suggest that the TNF-α (-G308A) polymorphism can be a risk factor for UGIB in the Brazilian population, and therefore, can potentially be a predictive factor for the severity of UGIB resulting from PPF in schistosomiasis." (PMID 36820674, 2023). "There are controversial reports regarding the influence of TNF-α on schistosomiasis pathogenesis." (PMID 36820674, 2023). "Also, the injection of GNPs into schistosomiasis-infected mice resulted in a significant downregulation of IL-1β and TNF-α expressions in the hepatic tissue of mice, thus improving liver dysfunction." (PMID 34944582, 2021). "Given the importance of IL-10 and TNF-α in schistosomiasis, this cross-sectional study was designed to determine possible links between single nucleotide polymorphisms (SNPs) in promoter regions of IL-10 and TNF-α genes and susceptibility to schistosomiasis." (PMID 34485462, 2020). "However, during the chronic phase of schistosomiasis, the levels of TNF-α, IFN-γ, IL-6, IL-4, IL-10, and IL-17A remained increased in the IUT and VEH groups." (PMID 30258438, 2018). "The protection correlated with the onset of oviposition and TNF-α-mediated goblet cell hyperplasia and mucus secretion, suggesting that these mechanisms are involved in enhanced immune protection to respiratory viruses during chronic murine schistosomiasis." (PMID 25398130, 2014). "Furthermore, elevated levels of tumor necrosis factor alpha (TNF-α) are present in schistosomiasis patients, and high TNF-α levels are known to induce TF expression on endothelial cells in vitro." (PMID 24385897, 2013). "From these data we conclude that IL-5 and TNF-α may participate in liver pathology in schistosomiasis." (PMID 23320145, 2012). "Considering that these former molecules were positively associated with S. mansoni parasite burden, as were TNF-α and RANTES, they may represent biomarker for the progression of liver pathology in schistosomiasis." (PMID 23320145, 2012). "This is mainly due to the fact that schistosomiasis is dominated by the Th1 immune response at 6–8 weeks and then reaches a peak, and subsequently, a large number of pro-inflammatory cytokines such as tumor necrosis factor, interleukin-1, and interleukin-6 appear." (PMID 35004354, 2021). "Several genes dysregulated by either or both species of schistosomes have been linked to inflammation and schistosomiasis-associated disease but have not been associated with cancer, at least in a direct manner, e.g. Tumor Necrosis Factor (TNF) or Nuclear Factor Kappa B subunit 1 (NFK-B)." (PMID 31341177, 2019). "The increase in TNFα is in disagreement with previous attempts by other investigator showing lower TNFα in CSF of SCS patients and similar TNFα in prefrontal cortex in schistosomiasis-infected mice at postnatal stage." (PMID 39959586, 2024).
schistosomiasis (continued). "A study in Brazil, a country considered endemic for schistosomiasis, suggested that Sm14 protects uninfected individuals against schistosomiasis by stimulating CD4+ T cells and producing higher IFN-γ and TNF-α." (PMID 39481080, 2024). "The impact of the expression of polymorphic variations in TNF-α and its effect on the severity of UGIB in patients with schistosomiasis needs to be better elucidated." (PMID 36820674, 2023). "The study sought to evaluate cytokine (IL-2, IL-4, IL-5, IL-10, TNF, and IFN-γ) profiles in the serum of children infected with schistosomiasis before and after treatment with praziquantel (PZQ)." (PMID 34239575, 2021). "The cytokine levels of TNF-α, IFN-γ, IL-6, IL-4, IL-5, IL-10, IL-13, and IL-17A in the sera of acute phase schistosomiasis were all significantly increased in the IUT and VEH groups compared with the UI group." (PMID 30258438, 2018). "High levels of TNF-α and IFN-γ are often implied in the pathogenesis of a severe form of human schistosomiasis, the hepato-splenic form, which could resemble Henderson's hypersplenomegaly syndrome (HSS)." (PMID 25398130, 2014). "Likewise, in schistosomiasis patients, severe disease is correlated with decreased production of type 2 cytokines and elevated levels of IFN-γ, TNF and nitric oxide." (PMID 24130499, 2013). "Therefore, owing to the small sample size, further studies are necessary to rule out the influence of TNF-α on schistosomiasis pathogenesis." (PMID 36820674, 2023).
diabetic cardiomyopathy (44 papers, 2011 to 2026). Diabetic cardiomyopathy is a disorder of the heart muscle in people with diabetes. "Mechanistically, inulin suppresses pro-inflammatory cytokines (e.g., IL-6, TNF-α), thereby attenuating systemic inflammation, preserving mitochondrial function, and inhibiting diabetic cardiomyopathy progression." (PMID 41601761, 2026). "Elevated inflammatory markers like CRP and TNF-α levels were observed in diabetic cardiomyopathy patients in line with our study." (PMID 39204151, 2024). "For example, intramyocardial inflammation (including increased expression of IL-6 or TNF-α) contributed to diabetic cardiomyopathy." (PMID 35898716, 2022). "In vivo study using the model of diabetic cardiomyopathy demonstrated that the inhibition of TNF-α can relieve left ventricle dysfunction by reducing myocardial inflammation and cardiac fibrosis mediated by TNF-α responses." (PMID 36012347, 2022). "IL-6, TNF-α and AGEs panel had AUC 0.924 for differentiating diabetic cardiomyopathy from DM-N (85% sensitivity and specificity)." (PMID 34046187, 2021). "Intramyocardial inflammation in diabetic cardiomyopathy has also been reported, as shown by increased expression of inflammatory cytokines (TNF-α and TGF-β1)." (PMID 34926700, 2021). "Isovitexin found in Gentiana lutea plant has also been implicated with endothelial inflammation in diabetic rats, where pro-inflammatory cytokine TNF-α production was blocked by isovitexin treatment, showing possible aide in diabetic cardiomyopathy." (PMID 32694996, 2020). "Studies unveiled that inhibiting p38MAPK activity in diabetic cardiomyopathy mouse models effectively lowers the levels of inflammatory cytokines such as TNF-α, IL6, IL1-β, and TGF-β1 in myocardial tissue, thus improving the left ventricular function of DCM mice." (PMID 40373162, 2025). "In the context of diabetes cardiomyopathy, our analysis unveiled a substantial upregulation in the expression of TNF-alpha (p < 0.001), IL-6 (p < 0.001), and NF-κB (p < 0.001) within the heart tissues of the vehicle-treated rats compared to their respective control groups." (PMID 39496097, 2024). "Furthermore, AuNP treatment reduced myocardial mRNA and protein levels of TNF-α in diabetic cardiomyopathy (DCM), resulting in a reduced intramyocardial inflammatory response and cardiac collagen content." (PMID 36060470, 2022). "Moreover, MSCs also have the capacity to decrease cardiac tumor necrosis factor α (TNF-α) and interleukin-1 expression which both are involved in the initiation and progression of diabetic cardiomyopathy." (PMID 33585587, 2020). "As such, it is possible that isovitexin which is found in kawakawa leaf extracts at significant levels, may also inhibit TNF-α production in injured endothelial tissue related to diabetic cardiomyopathy." (PMID 32694996, 2020). "Interestingly, in T1DM-induced diabetic cardiomyopathy, administration of an anti-TNF-α monoclonal antibody lessen cardiac TNF-α and IL-1β expression in correlation with cardiac collagen-I and -III content, and improvement of left-ventricle function." (PMID 28659798, 2017). "In the present study, diabetic cardiomyopathy is characterized by an decrease in the phosphorylation state of Akt and GSK-3β, which was associated with augmented cardiac inflammation as evidenced by increased NF-κB phosphorylation and TNF-α, IL-6 expression, as well as increased MPO activity." (PMID 21232147, 2011). "Cardiac expression of pro-inflammatory cytokines such as TNFα and IL6 often increases in settings of cardiac distress such as diabetic cardiomyopathy and acute MI, and this is necessary for tissue repair and healing." (PMID 31920673, 2019). "Another study compared the expression of inflammatory biomarkers like TNF alpha, IL-1beta, and IL-6 in diabetic cardiomyopathy mice in which MALAT1 was knockdown to a control group of diabetic cardiomyopathy mice where MALAT1 expression is intact." (PMID 29998127, 2018).
diabetic cardiomyopathy (continued). "In addition, a glucocorticoid (methylprednisolone) treatment reduced expression of TLR4/NF-κB signaling and IL-1β, IL-6, TNF-α, and ICAM-1 on T1DM-induced diabetic cardiomyopathy with I/R injury." (PMID 28659798, 2017). "Notably, in mouse models of diabetic cardiomyopathy, elevated expression levels of TNF-α and p-P38MAPK were noted." (PMID 40373162, 2025). "(2016) investigated the potential role of DOE in diabetic cardiomyopathy and found that DOE downregulated the activities of TNF-α and IL-1β, indicating that DOE might have protective potential for human against oxidative damage via inhibition of several pro-inflammatory factors." (PMID 32657196, 2020).
helminth infection (44 papers, 2006 to 2025). "In this study, while IL-6 and IL-8 were very high in all the subgroups at baseline, increased TNFα levels were associated with helminth infection (either egg positivity at baseline or with high Ascaris-specific IgE profile in antigen-stimulated assays)." (PMID 25209883, 2014). "With regards to cytokine production, we found a positive association of TNF production in response to LPS stimulation with helminth infections as well as with TIgE." (PMID 23365679, 2013). "In addition, TNF production in response to LPS stimulation was positively associated with the number of helminth infections with the highest LPS-TNF levels in participants with 3 or more infections." (PMID 23365679, 2013). "In helminth infections, TNFα serves a dual function: it facilitates the clearance of parasites by the immune system, but it can also induce tissue injury and excessive inflammation." (PMID 41026274, 2025). "Tumor necrosis factor (TNF) and IL-6 contribute to inflammatory signalling and immune cell recruitment, although their roles in helminth infection can be context-dependent." (PMID 41039483, 2025). "In helminth infections, TNF-α is involved in protective Th2 immune responses and promotes parasite expulsion." (PMID 40284708, 2025). "TNF-α has a critical role in the regulation of Th2 cytokine-mediated host protection against helminth infections." (PMID 36016178, 2022). "IL-10, a cytokine with broad immunoregulatory function, is known to inhibit the production of iNOS, IFN-γ, IL-12, TNF-α production and suppresses parasite killing in a variety of protozoan and helminth infections." (PMID 34539633, 2021). "Helminth infection can alter Th1/Th2 immune polarization, reduce systemic levels of Th1/Th17 pro-inflammatory cytokines (IL-4 over IL-17, TNF-α and IFN-γ), switch macrophages from M1 to M2 pattern, or change intestinal microbial diversity, all of which lead to increased insulin sensitivity." (PMID 35639713, 2022). "The frequency of TNF-α producing monocyte subsets were also analyzed in these cohorts to elucidate whether general helminth infection affects the functional activity of monocyte subsets." (PMID 33651797, 2021). "Interestingly, TNF-α lung expression was suppressed in the presence of helminth infection when compared to respective naive or P. aeruginosa-infected mice." (PMID 31673002, 2019). "Similarly, in our study, helminth infection significantly elevated IL-10 levels while concurrently reducing decreased TNF-α expression, indicating that helminth infection protects against the HFD-induced abnormal lipid metabolism via activation of immune responses in teleost." (PMID 40708918, 2025). "Chronic helminth infections mediate a modified Th2 immune response, resulting in reduced pro-inflammatory cytokines, such as IFN-γ and TNF-α, and an increase in anti-inflammatory cytokines, such as IL-10 and TGF-β." (PMID 35206272, 2022). "Despite costimulatory-derived signals by B cells seeming to favour Th2 cell development in helminth infection, effector B cells, termed as Be1, positively regulate Th1 cell differentiation via IFN-γ and tumor necrosis factor (TNF) production." (PMID 33983946, 2021). "Using TNF-α as a functional readout for monocytes, indicates that helminth infection alone does not affect monocyte function, whereas coinfection with helminths and TB increases TNF-α in both intermediate and non-classical monocytes." (PMID 33651797, 2021). "Cytokine ELISA data showed that helminth infection significantly inhibited LPS-, but not IL-1β-, induced TNF-α and IL-6 production, suggesting that helminth infection specifically inhibits the TLR4 signaling pathway." (PMID 25010669, 2014). "Although TNFα is not a typical Th2 cytokine since it mediates pathogenesis in a board range of Th1-mediated diseases, it participates in the regulation of Th2 cell–mediated protection during helminth infection has already been reported." (PMID 31862904, 2019).
helminth infection (continued). "Since the MyD88-mediated pathway plays a key role in IL-1R signaling, unimpaired IL-1β–induced TNF-α and IL-6 production by macrophages from helminth-infected host suggests that the effect of the helminth infection is not on MyD88-dependent signals, but is likely to be on the TRAM/TRIF pathway." (PMID 25010669, 2014). "Further real time quantitative RT-PCR analysis of colonic tissues showed the helminth-infection induced down-regulation of TNF-α expression in both wild-type and MyD88 knockout mice with H. polygyrus-infection, suggesting the impact of helminth infection on TNF-α expression is MyD88-independent." (PMID 25010669, 2014). "The group without evidence of helminth infection (egg-IgElo) had the lowest or undetectable levels of all pro-inflammatory (IL-6, IL8 and TNFα) median values in response to HIV-p24 and Ascaris-stimulation." (PMID 25209883, 2014). "To confirm whether type 2 cytokines IL-4, IL-5, IL-9, and IL-13 contributed to helminth-induced protection against TNF-α and IFN-γ shock, we compared the levels of cytokines in the presence or absence of the helminth infection." (PMID 38727220, 2024). "The frequency of TNF-α producing monocyte subsets was evaluated in PTB patients and CCs with and without helminth infection, to investigate whether helminth infection affects the functional activity of monocyte subsets." (PMID 33651797, 2021).
intracerebral hemorrhage (44 papers, 2011 to 2026). A cerebrovascular disorder characterized by bleeding into one or both cerebral hemispheres including the basal ganglia and the cerebral cortex. "Prior studies demonstrate that TNFα is associated with worse outcome and mortality in intracerebral hemorrhage." (PMID 33585095, 2021). "Furthermore, increased plasma TNFR1 and TNFR2 levels were associated with the risk of intracerebral hemorrhage, suggesting that TNF-mediated inflammation is associated with vascular changes preceding intracerebral hemorrhage." (PMID 33918875, 2021). "TNF-mediated inflammation could thus be associated with vascular changes preceding intracerebral hemorrhage." (PMID 32503645, 2020). "Previous reports also showed that IL-6 and TNF-α levels increased in TNFAIP3-/- sham groups of an intracerebral hemorrhage mouse model, suggesting that TNFAIP3 deficiency caused spontaneous inflammation in the mouse brain, which was consistent with our results in GMH pups." (PMID 32859236, 2020). "In brief, intracerebral hemorrhage can cause inflammatory reactions by activating PMNs, microglia, and other cells, which can upregulate the expression of TNF-α, MMP-9, and other inflammatory cytokines, thereby causing BBB destruction and cell swelling and aggravating cerebral edema." (PMID 32564011, 2020). "Under conditions of intracerebral hemorrhage, the associated elevation of TNF-α within the brain is primarily due to neutrophils; a systemic injection of minocycline within 6 hours of the insult reduced TNF-α and MMP-12 expression, microvessel loss, and extravasation of plasma proteins and edema." (PMID 21845170, 2011). "In murine intracerebral hemorrhage models, Cerebrolysin-treated animals exhibited significant reductions in IL-1β, IL-6, and TNF-α, as well as in aquaporin-4 (AQP4)—a main mediator of vasogenic edema." (PMID 40362194, 2025). "A recent study has clarified that overexpression of HSPA9 prevents inflammation in a rat model of intracerebral haemorrhage through inhibition of inflammatory cytokines such as TNF-α, IL-β, Bax, and increased Bcl-2 levels." (PMID 35258800, 2022). "Potential treatments for intracerebral hemorrhage aimed at reducing TNFα levels include anti-TNFα monoclonal antibodies and atorvastatin." (PMID 33585095, 2021). "In the brains of mice, intra-ipsilateral and contralateral infusion of the PDGFRβ inhibitor Greevec decreases the intracerebral hemorrhage-induced increase in TNF-α levels." (PMID 34122447, 2021). "TNFα is a pro-inflammatory cytokine release by neuronal macrophages, astrocytes, and microglial cells during intracerebral hemorrhage." (PMID 33585095, 2021). "We conducted a retrospective chart review of patients with spontaneous intracerebral hemorrhage with TNFα, CRP, VEGF, Hcy levels drawn on admission." (PMID 33585095, 2021). "Studies have shown that TNF-α downregulates the expression of microglia CD36, resulting in the loss of phagocytic capacity of microglia to phagocytosis of hematoma after intracerebral hemorrhage." (PMID 34956584, 2021). "Murine intracerebral hemorrhage models exposed to Cerebrolysin revealed significant reductions in pro-inflammatory markers such as IL-β, IL-6 and TNF-α as well as aquaporin-4, an important mediator for hematoma-induced vasogenic edema." (PMID 33143640, 2020). "Through the inhibition of the TLR4/NF-κB pathway, the secretion of TNF-α, IL-6, and IL-1β decreases, and the injury to the brain due to intracerebral hemorrhage can be attenuated." (PMID 33133217, 2020). "Metformin downregulated the expression levels of inflammatory cytokines (IL-1β, IL-4, and IL-6 and TNF-α) in intracerebral hemorrhage model rats." (PMID 32831980, 2020). "Inhibition of microglia inflammation by reduction of NF-κB activation and by the attenuation of TNF-α, IL-1β,IL-6, and reactive oxygen species (ROS) protects the brain from intracerebral hemorrhage and MDD." (PMID 30356873, 2018).